HPSE (heparanase)
Diseases named in the same sentence as HPSE in open-access papers (continued):
Sharing a sentence is not in itself a finding about the gene and the disease.
Sepsis (57 papers, 2013 to 2025). Sepsis is defined as life-threatening organ dysfunction caused by a dysregulated host response to infection. "In sepsis, tumor necrosis factor-α and angiopoietin-2, among others, induce heparanase expression and activation, which causes endothelial dysfunction and organ insult mediated by damage to heparan sulfate, a component of the endothelial glycocalyx." (PMID 39944316, 2025). "Heparanase is also overexpressed in some malignant tumors and is activated in sepsis, causing partial degradation of the glycocalyx, which further exacerbates the loss of glycocalyx components." (PMID 40255592, 2025). "Heparanase and the inflammatory response in sepsis also cause degradation of syndecan-1, another structural component of the glycocalyx." (PMID 39944316, 2025). "Particularly in humans, the endo-β-glucuronidase Heparanase-1 (Hpa-1) is decreased during sepsis and has been proposed as a biomarker to predict the risk of sepsis in adults." (PMID 36613805, 2022). "In other inflammatory settings, such as colitis, delayed-type hypersensitivity, inflammatory bowel disease and lung injury caused by sepsis, overexpression of heparanase was primarily noted in epithelial and endothelial cells." (PMID 34220822, 2021). "Remarkably, a recent study suggested the increase of HPSE mRNA expression as well as enzymatic activity in platelets of sepsis patients, which was associated with sepsis-associated mortality." (PMID 34987504, 2021). "Although the greatest protection was observed when animals were prophylactically treated with heparin or were deficient for heparanase (Hpse−/−), a protective effect was still observed when treatment was delayed to 24 h after sepsis induction." (PMID 30776153, 2019). "Heparan sulfate (HS) fragments belong to the class of danger/damage-associated molecular patterns liberated from endothelial-bound proteoglycans by heparanase during tissue injury associated with trauma or sepsis." (PMID 29616016, 2018). "In a mouse model of sepsis-associated inflammatory lung disease, rapid induction of heparanase activity was demonstrated in pulmonary microvascular endothelial cells." (PMID 28386074, 2017). "Heparanase inhibition prevented endotoxemia-associated glycocalyx loss and neutrophil adhesion and, accordingly, attenuated sepsis-induced acute lung injury and mortality in mice." (PMID 28386074, 2017). "The following paragraph aims to discuss the potential of the newly investigated but promising markers of endothelial damage, such as syndecan-1, heparan sulfates, heparanase, endocan, and angiopoietins as diagnostic tools in sepsis." (PMID 27699168, 2016). "Two studies indicate that heparanase expression is elevated during sepsis-associated pulmonary and renal failure." (PMID 27699168, 2016). "It has been reported that mice deficient in heparanase are protected from sepsis-induced acute lung injury and allergic inflammation, suggesting that heparan sulfate provides a pro-inflammatory cue." (PMID 26039697, 2015). "Administration of heparanase inhibitors 2 h prior to CLP attenuated sepsis-induced loss of glomerular filtration rate, demonstrating that heparanase activation contributes to early septic renal dysfunction." (PMID 24400155, 2013). "In vascular homeostasis, during sepsis, heparanase causes the glycocalyx to shed." (PMID 37614234, 2023). "Heparanase activation plays a role in sepsis-associated respiratory distress." (PMID 35160072, 2022). "Furthermore, increased heparan sulfate and heparanase levels in the serum of patients and mice with sepsis suggests an association between heparanase activity and increased expression of Ang-2." (PMID 36142913, 2022). "Similarly, the administration of heparanase inhibitors for 2 h during early sepsis in mice models attenuated the loss of glomerular filtration rate and attenuated the serum levels of IL-10." (PMID 36613805, 2022).
Sepsis (continued). "Heparanase is a β-d-endoglucuronidase that remodels the endothelial glycocalyx by degrading heparan sulfate in many diseases/conditions associated with systemic inflammation including sepsis, trauma, and major surgery." (PMID 28659919, 2017). "The vascular involvement in clinical manifestations associated with diabetes, sepsis, ischemia, artherosclerosis, and angiogenesis in cancer may be dictated in part by the interplay between eNOS and heparanase." (PMID 27505185, 2016). "Detection of urinary heparanase activity could serve as a prognostic biomarker in sepsis, identifying patients at risk for AKI onset and progression." (PMID 24400155, 2013). "We therefore hypothesized that sepsis is associated with activation of glomerular heparanase, contributing to the early onset of septic AKI." (PMID 24400155, 2013). "Moreover, when the expression of endogenous antagonist angiopoietin-2 (Ang-2) is increased, it displaces ang-1 from the endothelium-stabilizing receptor Tie2 in sepsis, inducing heightened heparanase expression, thus stimulating pathogenic sheddase of the endothelial glycocalyx." (PMID 36613805, 2022). "In a mouse model of sepsis, heparin protects the macrophage glycocalyx by inhibiting heparanase, in addition to its anticoagulant effect, and induces an anti‐inflammatory effect by inhibiting caspase‐11 activation by LPS." (PMID 40145013, 2025). "We have previously shown that in sepsis and COVID-19, the final common pathway of eGC damage appears to be the activation and release of the heparan sulphate-degrading enzyme heparanase." (PMID 38598083, 2024). "HPSE expression and activity were shown to increase in platelets during clinical sepsis at both the transcriptomic and proteomic levels." (PMID 38892129, 2024). "Heparanase plays a crucial role in the pathology of sepsis, and its inhibition can significantly relieve related symptoms." (PMID 38810101, 2024). "Platelets are a cellular source of heparanase, with expression and activity of HPase increased in sepsis." (PMID 37259415, 2023). "In an LPS-induced sepsis mouse model, pulmonary endothelial heparanase was activated in a TNF-α dependent manner." (PMID 36865384, 2023). "The role of heparan sulfate degradation in sepsis, mediated by heparanase-1, has been solidified through numerous preclinical and clinical studies." (PMID 38117435, 2023). "For instance, sepsis-related activation of the glycosaminoglycans sheddase heparanase-1 is dependent upon endothelial-derived TNF-α." (PMID 38117435, 2023). "Cell surface HS modulates several of the mechanisms involved in sepsis such as pathogen interactions with the host cell and neutrophil recruitment and is a target for the pro-inflammatory enzyme heparanase." (PMID 37259415, 2023). "Heparanase-1 is activated during sepsis, contributing significantly to the degradation of the glycocalyx." (PMID 38117435, 2023). "Intestinal injury in a mouse model of sepsis was reduced after inhibition of heparanase by unfractionated heparin." (PMID 37259415, 2023). "Heparanase is the only mammalian enzyme with activity on HS and is involved in sepsis-mediated lung, kidney, and intestinal injury through EG erosion." (PMID 35763350, 2022). "Elevated heparanase expression has been shown in several inflammatory pathologies, such as cardiovascular disease, diabetes, kidney disease and sepsis." (PMID 35887981, 2022). "We observed that heparanase activity is significantly higher in the plasma of children with sepsis than healthy controls, similar to adults with sepsis." (PMID 35763350, 2022). "Research supports that various glycosidases, including heparanase and hyaluronidase, are involved in the degradation of glycocalyx and play an important role in the pathophysiological mechanism of sepsis." (PMID 36062176, 2022). "Heparanase-1 (Hpa-1) is the enzyme primarily responsible for the injurious degradation of the major eGC component, heparan sulfate (HS), and is upregulated in sepsis." (PMID 34817751, 2021).
Sepsis (continued). "For example, heparanase was shown to promote ulcerative colitis, acute pancreatitis, acute vasculitis, acute glomerulonephritis, sepsis, and hypersensitive pneumonia." (PMID 34220822, 2021). "We therefore measured hyaluronidase, heparanase, and chondroitinase activities in plasma of patients with COVID-19 compared with either healthy controls or patients with sepsis." (PMID 34314391, 2021). "By contrast, Heparanase-2 (Hpa-2), a protein that has been described as a protective antagonist of Hpa-1, is suppressed in murine sepsis models, suggesting imbalance of eGC-regulating proteins in sepsis." (PMID 34817751, 2021). "Activation of heparanase was also observed early in the sepsis-induced AKI in mice and correlated with higher pro-inflammatory cytokine levels." (PMID 32974364, 2020). "Detectability of heparanase in the urine also supported its potential as an important biomarker in sepsis–AKI." (PMID 32974364, 2020). "Heparin is postulated to protect the glycocalyx from degradation in sepsis by serving as an inhibitor of heparanase, which sheds heparan sulfate from the endothelial glycocalyx." (PMID 30654825, 2019). "For example, in sepsis heparanase is upregulated by tumor necrosis factor-α (TNF-α) and induces shedding of the glycocalyx, thereby exposing the endothelial surface and adhesion molecules which facilitate neutrophil recruitment." (PMID 31110966, 2019). "Heparin can inhibit heparanase activity and protect from shedding of glycocalyx components, even during inflammatory states such as sepsis." (PMID 31456998, 2019). "During sepsis, the glycocalyx is degraded via inflammatory mechanisms such as metalloproteinases, heparanase, and hyaluronidase." (PMID 30654825, 2019). "Heparanase contributes to various inflammatory diseases including delayed hypersensitivity, vascular injury, chronic colitis, Crohn's disease, sepsis, rheumatoid arthritis, atherosclerosis, and diabetes." (PMID 31110966, 2019). "Heparanase is a glucuronidase responsible for degradation of the glycocalyx network, and possibly mediating renal and lung injury during sepsis, as demonstrated in animal models." (PMID 31456998, 2019). "Heparanase, a heparan sulfate-specific glucuronidase, mediates the onset of renal dysfunction and lung injury during sepsis." (PMID 27699168, 2016). "In conclusion, the findings of our current study indicate that peptide 19–2.5 interacts with heparanase, which is elevated in murine and human sepsis and consecutively attenuates the generation of circulating HS-fragments in systemic inflammation." (PMID 26600070, 2015). "It has also been reported that heparanase inhibition prevents sepsis-induced mortality and acute lung injury (ALI) in mice." (PMID 26039697, 2015). "In summary, our data indicate for the first time that plasma heparanase level and activity are elevated in murine and human sepsis." (PMID 26600070, 2015). "Thereby, heparanase liberates highly potent circulating heparan sulfate-fragments (HS-fragments) and triggers the fatal and excessive inflammatory response in sepsis." (PMID 26600070, 2015). "Recently, heparanase inhibitory peptides derived of TFPI-2 were demonstrated by us to inhibit heparanase procoagulant activity and attenuate sepsis in mouse models." (PMID 25386347, 2014). "This activity normalized within 24 h, suggesting that renal heparanase activation was an early event in the onset of experimental sepsis." (PMID 24400155, 2013). "We now expand these findings beyond lung injury, demonstrating that glomerular heparanase is induced in experimental sepsis and contributes to the onset of septic renal dysfunction." (PMID 24400155, 2013). "To investigate renal heparanase activation during sepsis, we chose to employ CLP, the gold-standard model for experimental sepsis." (PMID 24400155, 2013). "Kidney dysfunction occurred early in murine sepsis, coincident with the observed increase in glomerular heparanase expression and activity." (PMID 24400155, 2013).
Sepsis (continued). "Heparanase, a heparan sulfate-specific glucuronidase, mediates the onset of pulmonary neutrophil adhesion and inflammatory lung injury during early sepsis." (PMID 24400155, 2013). "Our data demonstrate that glomerular heparanase activity increases in early murine sepsis and mediates the onset of renal dysfunction." (PMID 24400155, 2013). "Heparanase, an enzyme that degrades heparan sulfates, may be enhanced under stress situations such as sepsis, suggesting a potential second-hit mechanism contributing to thrombotic complications in APS." (PMID 40643541, 2025). "However, upstream of HPSE upregulation and release, only a few specific signalling pathways have been identified, all of which are pathophysiologically relevant in sepsis." (PMID 38598083, 2024). "During sepsis, heparanase increases and induces HS shedding." (PMID 36865384, 2023). "During sepsis, the glycocalyx may be shed by various mechanisms, such as metalloproteinases, heparanase, and hyaluronidases." (PMID 37614234, 2023). "Interestingly, heparanase activity and HS levels are elevated in adults hospitalized with severe COVID-19 similar to patients with sepsis." (PMID 35763350, 2022). "Interestingly, animal models of sepsis have demonstrated that glycocalyx degradation involved the activation of endothelial heparanase, via TNF-α-dependent mechanisms." (PMID 35347344, 2022). "Notably, heparanase activity increases as an acute response in models of ischemic stroke and sepsis, and promotes degradation of the endothelial glycocalyx which in turn increases immune cell infiltration and associated inflammation." (PMID 33971986, 2021). "It has been previously reported that heparanase is highly expressed in a variety of inflammatory diseases, including ulcerative colitis, acute pancreatitis, acute vasculitis, acute glomerulonephritis, hypersensitivity pneumonia and sepsis." (PMID 34220822, 2021). "The glycocalyx functions as a barrier to circulating cells; however, enzymatic degradation, especially HS degradation by heparanase (HPSE), an endo-β-glucuronidase, induces inflammatory responses in conditions such as sepsis, proteinuria, and diabetic nephropathy." (PMID 33127645, 2020). "Several studies demonstrated important proinflammatory functions of heparanase, mediating inflammatory and sepsis processes, mainly in lung and pancreas infections and inflammations, and also demonstrated a possible role of heparanase in atherosclerosis processes." (PMID 29226146, 2017). "Moreover, because heparanase helps drive the progression of other diseases (e.g., diabetes, diabetic nephropathy, arthritis, colitis, sepsis, atherosclerosis), these drugs hold potential to impact public health." (PMID 28359266, 2017). "Delayed heparanase inhibition 24 h after the onset of sepsis attenuated pulmonary endothelial hyperpermeability, suggesting that heparin is a lung-protective intervention even in established sepsis." (PMID 27699168, 2016). "Heparanase inhibition by NAH prevented endotoxemia-associated glycocalyx loss and neutrophil adhesion and, accordingly, attenuated sepsis-induced acute lung and renal injury and improves survival in mice subjected to polymicrobial sepsis." (PMID 27699168, 2016). "We hypothesized that peptide 19–2.5 interacts with heparanase and/or HS, thereby reducing the levels of circulating HS-fragments in murine and human sepsis." (PMID 26600070, 2015). "Thus, our study aimed to investigate peptide 19–2.5 interaction with heparanase and HS-fragments in murine and human sepsis." (PMID 26600070, 2015). "Furthermore, when HPSE activity is blocked with competitive inhibitors, sepsis-induced glomerular dysfunction and inflammation are attenuated in a polymicrobial sepsis mouse model." (PMID 25295599, 2014). "Future human studies of urinary heparanase activity in the critically ill could therefore have significant clinical impact in sepsis, addressing a major need in critical care medicine." (PMID 24400155, 2013).
Sepsis (continued). "We hypothesized that glomerular heparanase is similarly activated during sepsis and contributes to septic acute kidney injury (AKI)." (PMID 24400155, 2013). "The mechanisms underlying heparanase-mediated renal dysfunction are disparate from those underlying heparanase-mediated ARDS, demonstrating pathophysiologic heterogeneity of organ injury during sepsis." (PMID 24400155, 2013). "It is more likely that eGC in sepsis is affected by additional and/or more complex mechanisms, which may explain the lack of clinical efficacy of several targets that (at least in theory) should also diminish heparanase release." (PMID 38598083, 2024). "Notably, heparanase inhibition seems to be protective also after sepsis onset." (PMID 27699168, 2016). "Thus, peptide 19–2.5 may be a potential anti-inflammatory agent in sepsis by interacting with heparanase and circulating HS-fragments." (PMID 26600070, 2015). "Thus, new anti-inflammatory agents interacting with heparanase and reducing the levels of circulating HS-fragments may be promising candidates for sepsis therapy." (PMID 26600070, 2015). "The specific mechanisms included increases in the lactate level and histone H3 lysine 18 lactylation (H3K18la) induced by sepsis, which activated EGR1/HPSE signaling, promoting the degradation of the glycocalyx barrier." (PMID 39721014, 2025). "N-acetyl heparin has been referred to as non-anticoagulant heparins (NAH) in many studies, shown to protect against sepsis-induced lethality and organ damage by targeting HMGB1/LPS complex, heparanase, and histones." (PMID 36865384, 2023). "Not all targets in the sepsis pathway are related to glycocalyx, and there are 6 targets (SI, ROCK1, TLR4, VEGFA, HPSE, and LGALS3) of active ingredients not only related to glycocalyx, but also involved in the sepsis pathway." (PMID 36062176, 2022). "Administration of heparanase inhibitors two hours prior to CLP attenuated the deleterious consequences of sepsis, suggesting that glomerular heparanase is active during sepsis and contributes to septic renal dysfunction via uncharacterized mechanisms." (PMID 28388547, 2017). "We found that urinary indices of heparanase activation were maximal 4 h after CLP, coincident with the so-called “hyperdynamic” phase of sepsis (normal arterial blood pressure, elevated heart rate) often characteristic of AKI onset." (PMID 24400155, 2013). "Here, a novel heparanase inhibitor CV122 is rationally designed and synthesized, and its therapeutic potential for sepsis with Lipopolysaccharide (LPS) and Cecal Ligation and Puncture (CLP)‐induced sepsis mouse models are evaluated." (PMID 38810101, 2024). "In this work, the authors noted that the mice pre-treated with heparin or the non-anticoagulant heparanase inhibitor N-desulfated/re-N-acetylated heparin avoid the LPS-induced eGC shedding, thus attenuating sepsis-induced inflammatory lung injury." (PMID 36613805, 2022). "These reported data suggest that heparanase inhibition, especially with NAH, may be a promising therapeutic approach in sepsis therapy." (PMID 27699168, 2016). "The relevance of heparanase activation to nonpulmonary organ dysfunction during sepsis, however, remains unexplored." (PMID 24400155, 2013). "Upregulation of heparanase was reported in different inflammatory and autoimmune conditions including, among others, delayed type hypersensitivity (DTH), graft vs. host disease (GVHD), inflammatory bowel disease (IBD), rheumatoid arthritis (RA), type 1 diabetes, atherosclerosis and sepsis." (PMID 24465803, 2014). "Specifically, the authors induced polymicrobial sepsis in mice using cecal ligation and puncture (CLP) in the presence or absence of competitive heparanase inhibitors (heparin or nonanticoagulant N-desulfated re-N-acetylated heparin)." (PMID 28388547, 2017).